SETD1B (SET domain containing 1B, histone lysine methyltransferase)
Diseases named in the same sentence as SETD1B in open-access papers (continued):
Sharing a sentence is not in itself a finding about the gene and the disease.
tumor (16 papers, 2020 to 2025). "Mutations in SETD1B were also strongly associated with increased tumor infiltration with CD8+PD-1+TOX+ T cells, highlighting a potential link between this genetic alteration and immune recognition." (PMID 38653864, 2024). "Altogether, we identified a promising therapeutic agent, Trip, that inhibited tumor progression in our preclinical mouse models of HCC by targeting SETD1B to suppress the stemness of LCSC." (PMID 40860182, 2025). "It is understood that underexpression of both miRs leads to an overexpression of SETD1B, and thus, an increase in transcriptional activation leading to overexpression of oncogenes, which is necessary for a tumor or hyperplastic cell." (PMID 38994952, 2024). "In tumor-bearing mice, the inhibition of SETD1B suppressed the H3K4me3 level at the Nos2 promoter region and diminished the inducible nitric oxide synthase expression in myeloid-derived suppressor cells." (PMID 32636801, 2020). "First, we found a high and significant correlation between ZEB1 and SETD1B (rs = 0.523, p < 0.001) in this tumor group." (PMID 32094334, 2020). "The SETD1B-H3K4me3 epigenetic axis has been reported to contribute to increased iNOS expression in tumor-induced myeloid-derived suppressor cells to render T cell low responsive to antigen stimulation." (PMID 32094334, 2020). "A lower expression of SETD1B in older gulls thus suggests a method for suppressing uncontrolled cell growth and thus neoplasia." (PMID 32821278, 2020). "Thus far, our results have demonstrated the critical role of SETD1B in defining stem-like characteristics in LCSCs and tumor progression, suggesting potential therapeutic benefits in targeting this molecule." (PMID 40860182, 2025). "More importantly, we demonstrated that SETD1B can be targeted for degradation by triptolide, a naturally occurring diterpenoid epoxide found in the gold vine, which leads to remarkable control of tumor growth, even when used as a monotherapy in our preclinical model of HCC." (PMID 40860182, 2025). "Upregulation of SETD1B was found to activate iNOS expression in tumor-induced myeloid-derived suppressor cells, which could provide a foundation for establishing an effective approach for improving the efficacy of cancer immunotherapy by targeting SETD1B." (PMID 34201935, 2021). "We demonstrated that SETD1B, driven by MAZ, enhances stem characteristics by promoting anchorage-independence, cellular adhesion, tumor sphere formation, and growth via the surface glycoprotein CD24." (PMID 40860182, 2025). "Among these ten genes, the expression levels of SETD1B, ACSF2, MUC1, KLHL24, PML, MT1G, and GPT2 were higher in tumor tissues than those in normal tissues, while HIC1, AKR1C1, and LOC390705 were lower expressed in tumor tissues." (PMID 35071242, 2021). "This was further corroborated by the spatial transcriptomics (HRA000437) of patient tumor specimens, which showed a clear difference in SETD1B expression in HCC as opposed to its adjacent normal tissues." (PMID 40860182, 2025). "Indeed, further pathological analyses showed reduction of SETD1B, CD24, N-cadherin and Ki67 following Trip treatment in the tumor xenografts, but reduction of these proteins was no longer seen with SETD1B KD." (PMID 40860182, 2025).
cancer (14 papers, 2019 to 2025). A tumor composed of atypical neoplastic, often pleomorphic cells that invade other tissues. "SETD1B is also overexpressed in clear cell renal cell carcinoma (ccRCC), has been associated with cancer metastasis and has been reported as a promising prognostic indicator for ccRCC." (PMID 34201935, 2021). "The fourth transcript was linked to SETD1B, which supports mitotic processes and is overexpressed in several cancer types." (PMID 32821278, 2020). "Our unbiased pan-cancer expression analysis revealed that SETD1B levels were significantly altered in a number of cancer tissues compared with their respective normal counterparts." (PMID 40860182, 2025). "These eight transcripts were linked to the following cancer‐related genes: TRIM33, USP6, PRDM16, SETD1B, MLLT3, KEAP1, CHD2, and DCAF12L2." (PMID 32821278, 2020). "Biological variables associated to a high risk of progression included CIP2A levels, the expression levels of the polycomb group BMI1 gene, the activation of beta-catenin, specific gene signatures, and mutations in cancer-associated genes such as ASXL1, IKZF1, RUNX1, SETD1B, GATA2, MLL, and UBE2A." (PMID 31709190, 2019). "This is reflected by the association of SETD1B levels with the global stemness signature as KD of SET1DB simultaneously altered the expression of characteristic stemness marker genes, suggesting that SETD1B is capable of systematically reprogramming HCC cells into pernicious cancer stem cells." (PMID 40860182, 2025). "Among these, WDR66, SETD1B, and MLXIP were novel markers for cancer metastasis and involved in epithelial-mesenchymal transition (EMT) 65-67." (PMID 36632223, 2023). "Moreover, there is only speculation about SETD1B ́s role in cancer and EMT." (PMID 32094334, 2020). "SETD1B takes part in methylation of the histone H3 tail at lysine 4 (H3K4), an epigenetic mechanism that regulates transcription activation; changes in the degree of DNA methylation, chromatin structure, and post-translational modifications of histones may lead to the development of cancer." (PMID 38994952, 2024). "Conversely, perturbations that may promote aberrant stem cell-like activity and impair differentiation (cancer-promoting genes) included bromodomain-containing proteins (BRD1, BRD2), histone acetyltransferases (EP300), and histone lysine methyltransferases (KMT2C, NSD1, SETD1B)." (PMID 38472198, 2024).
neurodevelopmental disorder (7 papers, 2019 to 2025). A behavioral and cognitive disorder with onset during the developmental period that involves impaired or aberrant development of intellectual, motor, or social functions. "Genetics referral at 10 years of age due to her persistent and severe symptomatology led to exome sequencing, which identified a pathogenic variant in SETD1B causing SETD1B-related neurodevelopmental disorder." (PMID 39695270, 2025). "SETD1B adds to a growing list of chromatin modifying genes implicated in neurodevelopmental disorders." (PMID 34345025, 2021). "SETD1B is also a histone methyltransferase associated with neurodevelopmental disorder." (PMID 36117209, 2023). "Nevertheless, it is tempting to speculate that sex-linked traits could affect susceptibility to clinical penetrance and spectrum of SETD1B variants, as female-protective effects have been proposed for other neurodevelopmental disorders." (PMID 34345025, 2021). "We examined whether the DNA methylation signature of SETD1B-related syndrome overlaps with that of other neurodevelopmental disorders or syndromes, which in some cases, are caused by mutations in the members of the epigenetic machinery." (PMID 31685013, 2019). "Notably, although these genes have not been demonstrated to be directly associated with ALS in previous studies, NR4A1 and DRD4 are reported in AD, ACSL4 seems to be a biomarker of ferroptosis, and SETD1B is associated with syndromic neurodevelopmental disorder." (PMID 35873477, 2022). "In contrast, genes downregulated in SMS cortical neurons are involved in anatomical structure and multicellular organism development, including genes implicated in neurodevelopmental disorders (i.e., CHD4, UBE3B, KDM5B, and SETD1B)." (PMID 40882620, 2025). "Also, higher methylation at cg09709951 has been found to be related to neurodevelopmental disorder related to SETD1B gene in children." (PMID 39773758, 2025). "The specificity of the DNAm signature was highlighted by the lack of signature in patients carrying a deletion that did not include SETD1B or in a patient carrying a duplication of the region or patients with other neurodevelopmental disorders or syndromes." (PMID 31685013, 2019). "Only two probands (11%) with genetic diagnoses (SETD1B (ID10), ERF (ID18)) had CAS without co-occurring neurodevelopmental disorder diagnoses." (PMID 36117209, 2023).
SETD1B also shares sentences with these, for which no sentence is quoted: autism (3 papers); breast carcinoma (3); endometrial cancer (3); Hyperglycemia (2); Kabuki syndrome (2); pancreatic cancer (2); breast tumor (1); chronic myeloid leukemia (1); clear cell renal cell carcinomas (1); CNS lymphomas (1); craniosynostosis syndrome (1); hepatocellular carcinoma (1); Hunter–McAlpine syndrome (1); infection (1); intellectual developmental disorder with seizures and language delay (1); myeloproliferative neoplasm (1); myoclonic absences (1); Noonan syndrome (1); Obesity (1); polycythemia vera (1); primary ciliary dyskinesia (1); psychosis (1); renal carcinoma (1); renal cell carcinoma (1); Seizure (1); speech disorder (1); Tatton-Brown-Rahman syndrome (1); X-linked intellectual disability (1).